CXCL1 (C-X-C motif chemokine ligand 1)
Diseases named in the same sentence as CXCL1 in open-access papers (continued):
Sharing a sentence is not in itself a finding about the gene and the disease.
tumor (continued). "The oncogenic function of CXCL1 in HCC was confirmed by xenograft tumor assays in nude mice." (PMID 27542259, 2016). "CBRH‐7919 cells carrying CXCL1 siRNA resulted in decreased tumor growth in nude mice." (PMID 27682863, 2016). "In addition to IL-6, TAF overexpression of CXCL1 (GRO-alpha) has been recently shown to induce tumor cell invasion and enhance chemotherapeutic resistance." (PMID 27515302, 2016). "And down-regulation of CXCL1 led to strongly preventing from tumor growth in vivo." (PMID 27472713, 2016). "It was also reported that loss of TGF-β signaling promoted CXCL1 and CXCL5 secretion, which increased migration of CD11b+ Gr-1+ MDSC to the tumor tissues, and played indirect roles in increasing the number of T helper 17 (Th17) cells which have a pro-tumorigenic effect." (PMID 27136535, 2016). "In tumor cells, CXCL1 expression was mainly localized to the cytoplasm." (PMID 27542259, 2016). "In tumor tissues, miR-200a levels were inversely proportional to CXCL1 mRNA." (PMID 27542259, 2016). "Collectively, the authors proposed that Mincle pathway may support tumor progression in PDA independently of CXCL1." (PMID 27551523, 2016). "We evaluated whether knockdown of CXCL1 by RNA interference (RNAi) could suppress tumor growth in vivo." (PMID 27682863, 2016). "Furthermore, quantitative PCR analysis showed that CXCL1 expression in 3LL/shCXCL1 tumor tissues was significantly lower than that in 3LL/NC tumor tissues." (PMID 27446967, 2016). "CCL2, CXCL1 and CXCL2 expressed by IECs, stromal and tumor cells during CRC possess pro-tumoral capacities since they chemoattract myeloid cells including neutrophils and tumor-associated macrophages, and stimulate angiogenesis." (PMID 27344176, 2016). "Furthermore, knocking down CXCL1 expression in 3LL cells significantly hindered tumor growth by inhibiting recruitment of neutrophils from peripheral blood into tumor tissues." (PMID 27446967, 2016). "We further investigated the effect of CXCL1 knockdown on tumor cell growth in vivo." (PMID 27682863, 2016). "Expression of CXCL1 was significantly higher in alcohol-fed DEN-injected mice suggesting that CXCL1 signaling may be involved in promoting tumor growth in this experimental model." (PMID 26888602, 2016). "Given that CXCL1 induces cancer growth and invasion, the anti-tumor activities of HVJ-E+poly I:C may be cancelled by the pro-tumorigenic properties of CXCL1." (PMID 27259252, 2016). "CXCL1 also plays a vital role in multiple tumor progression." (PMID 26506233, 2015). "To test whether CXCL1 levels correlated with in vivo tumorigenicity, we performed murine tumor xenograft assay." (PMID 26104296, 2015). "Next, we tested whether CXCL1 is responsible for the increased tumour growth supported by vascularization and infiltration." (PMID 25734337, 2015). "Thus, STAT3 functions as tumour suppressor by sequestering NF-κB in the cytoplasm and thereby reducing NF-κB-dependent CXCL1 transcription." (PMID 25734337, 2015). "Notable instances of microRNA regulation of the tumor microenvironment in lung cancer include the repression of the angiogenic program by IL-8, ICAM and CXCL1 through the lung tumor cell mediated exosomal release of miR-192 with a consequent reduction in metastatic burden and tumor colonization." (PMID 25743773, 2015). "It is reported that CXCL1 boosts tumor angiogenesis and development." (PMID 26257076, 2015). "Moreover, a remarkable reduction of MDSCs cell populations in tumor and immune organs by PD-1 blockade was observed, which can be attributed to the decrease of CXCL1." (PMID 26573233, 2015). "To investigate whether CXCL1 is the central angiogenesis and tumour-promoting factor in our model and a potential therapeutic target, we treated the mice with SB225002, a small-molecule antagonist of CXCR2." (PMID 25734337, 2015).
tumor (continued). "Mast cells can exert pro-tumorigenic effects by secreting factors like VEGF, angiopoietin-1, CXCL1, and IL-8 that promote tumor angiogenesis, as well as growth factors such as PDGF, NGF, SCF, FGF2, and proteases that facilitate tumor cell growth and metastases." (PMID 24455486, 2014). "IFN-γ and TNF-α reversed the effect of CXCL1, but were less efficient in suppressing tumor growth." (PMID 25587026, 2014). "Consistent with previous studies, CXCL1 was expressed in the tumor epithelium and in the stroma." (PMID 25344051, 2014). "Likewise, angiogenesis-related IL-8 levels often elevated in tumor samples of patients with NSCLC can be regulated by miR-200 which also targets growth regulated alpha protein (CXCL1) secreted by the tumor endothelial and cancer cells." (PMID 24744457, 2014). "To determine whether the increased tumor recurrence was related to changes in patient survival, we analyzed the patient cohort for relationships between stromal CXCL1 RNA and survival." (PMID 25344051, 2014). "When pG/pI6-mice were inoculated with tumor cells, CXCL1 promoted tumor growth." (PMID 25587026, 2014). "Similarly, LPS stimulated macrophages from scramble controls produced ~24 ng/mL and those from SEMA7A silenced DA-3 tumor-bearers' macrophages produced 16.8 ng/mL of CXCL1." (PMID 24550834, 2014). "Next, we evaluated whether p65 and p50 nuclear translocation in doxorubicin-treated tumor specimens was associated with an increase in the expression of NF-κB target genes TNFAIP3, ICAM-1 and CXCL-1." (PMID 24344116, 2014). "Chemokines, including chemokine (C-X-C motif) ligand 1 (CXCL1), may regulate tumor epithelial-stromal interactions that facilitate tumor growth and invasion." (PMID 23815949, 2013). "Knowledge of the role of CXCL1 in tumor progression may facilitate the design of new therapeutic approaches that inhibit tumor cell growth through selective perturbation of CXCL1 function." (PMID 23815949, 2013). "Interestingly, tumor-adjacent urothelia also expressed high levels of CXCL1, suggesting that in urothelial components, early molecular changes occur well before morphological changes become evident." (PMID 23815949, 2013). "For instance, cancer cells that overexpress CXCL1 and 2 were found to be more primed for survival at metastatic sites, and are capable of attracting CD11b(+)Gr1(+) myeloid cells into the tumor that enhance cancer cell survival and enhance their chemoresistance and metastatic ability." (PMID 24405819, 2013). "CXCL1, 2, 4, and 10 are chemokines that have been studied extensively in regard to their role in inflammation, development, angiogenesis, and neoplasia." (PMID 22355249, 2012). "Other findings suggest that CXCL1 or CXCL8 signalling may reduce tumour growth by promoting senescence through CXCR2." (PMID 21298036, 2011). "It was inferred from microarray analyses of tumour cell-MSC co-cultures that several cytokines may be expressed in the tumour cells that act to promote these effects: CXCL1, CXCL5 and CXCL6, IL-6 and IL-8." (PMID 21902837, 2011). "Also CXCL1 has recently been shown to promote tumor growth and angiogenesis in different tumor types." (PMID 18578857, 2008). "Moreover, the authors observed that PGE2 promoted tumor growth in vivo by induction of CXCL1 expression resulting in increased tumor microvessel formation." (PMID 18578857, 2008). "In addition, several of our invasion-specific signature genes are chemokines including CXCL1, CXCL2, and IL-8 which have been implicated in the promotion of tumor-associated angiogenesis, a critical feature of invasive tumors." (PMID 17611626, 2007). "In a study on CXCL1 promoting the mutual activation of cancer-associated fibroblasts and OSCC cells, the results showed that CXCL1 neutralizing antibody and CXCR2 antagonist SB225002 attenuated the invasion-promoting effect of CAF-CM, confirming the importance of CXCL1 in tumor invasion." (PMID 41445742, 2025).
tumor (continued). "Additionally, CXCL1 expression in tumor tissues of HFD mouse was higher than that in LFD mouse." (PMID 40841364, 2025). "Consequently, blocking the CXCL1/CXCR2 signaling axis in tumor cells could be a promising approach to limit invasion and metastasis in a wide subset of CRC patients." (PMID 40943634, 2025). "Notably, Vegfa macrophages and Proinflammatory macrophages exhibited downregulation of tumor angiogenesis and protumorigenic genes (e.g., Cxcl3, Cxcl1, S100a8, SPP1) and upregulation of immune cell recruitment‐associated genes (e.g., Cxcl9, Ccl5, Ccl8) in mRNA‐treated groups." (PMID 39761175, 2025). "Furthermore, while our results suggest that CAF-derived signals are able to enhance neutrophil recruitment, we also acknowledge that chemokines secreted by tumor cells, such as CXCL1 and IL-8, may also play a role." (PMID 41035818, 2025). "Moreover, in many cancers, the expression of CXCL1 may correlate with tumor dimensions, tumor grade, and tumor-node-metastasis (TNM) stage." (PMID 39582536, 2024). "Therefore, high CXCL1 expression in the tumor is unfavorable." (PMID 38673949, 2024). "On the contrary, CXCL5, CXCL1 and CXCL2 have a tumor-promoting effect because they recruit MDSCs, which can play an immunosuppressive role by suppressing the immune function of lymphocytes through the secretion of Arg-1 and iNOS, and CXCL1 and CXCL2 also reduce the number of CD8+ T cells." (PMID 39007138, 2024). "Also, CXCL1 induces the recruitment of endothelial progenitor cells (EPC) into the tumor niche." (PMID 38673949, 2024). "Moreover, the CXCL1/CXCR2 axis is still thought to be closely related to tumour resistance." (PMID 37037815, 2023). "Therefore, CXCL8 can recruit suppressor cells to the tumor microenvironment by recognizing CXCL1." (PMID 36647133, 2023). "Likewise, GRO/CXCL1 can promote tumor growth and angiogenesis and regulate UM invasion." (PMID 37509362, 2023). "Notably, CXCL1 and CXCL8, which are the key functional genes in the hallmark pathway of EMT, are essential for the activation and trafficking of inflammatory mediators as well as tumor progression and metastasis." (PMID 37940972, 2023). "CXCL1 expression in the tumor may also be increased by recruited monocytes." (PMID 37408240, 2023). "Moreover, CXCR1 and CXCR2 are differentially expressed in human tissues, though in mouse, CXCR2 is the predominant receptor mediating response to the murine chemokine ligands during inflammation, angiogenesis, and tumor growth (CXCL1,2,3 and 5, also known as KC, MIP2α, MIP2β, and LIX)." (PMID 37270599, 2023). "It has previously been hypothesized that lung cancer cells express and release large levels of CXCL1 and that knocking down the angiogenic CXC chemokine suppresses tumor growth in animals by inhibiting infiltration of tumor-associated neutrophils into tumor tissues from peripheral blood." (PMID 36164329, 2022). "In addition, CXCL1 was also an important component of the tumor microenvironment, which was significantly associated with the abundance of B cells, DC cells, CD8 + T cells, etc., regulating tumor microenvironment." (PMID 36581948, 2022). "Therefore, such modified T cells could be recruited to solid tumors with an elevated concentration of CXCL1, which would result in the initiation of an anti-tumor immune response." (PMID 35054978, 2022). "To date, increasing evidence has demonstrated that the expression levels of CXCL1 and CXCR2 are frequently upregulated in several human cancers, and CXCL1 may serve as a source of autocrine/paracrine signal for the malignant process in the tumor microenvironment." (PMID 35764974, 2022).
tumor (continued). "Further, the supernatants derived from the medium of CXCL1 overexpressing PHM1-41 cell can behave as a promoting mediator for the growth and migration of HeLa cells, indicating that CXCL1-paracrine interaction plays a crucial role in tumor-associated malignant behaviors." (PMID 35764974, 2022). "Notably, Osmrhigh CAFs express higher levels of inflammatory signals such as Il6, Ccl7, Ccl2 and Cxcl1 in animal models of PDA, OSMR is expressed at increased levels in human PDA and is associated with a tumour-promoting immune infiltrate and worse patient outcome." (PMID 34921158, 2021). "In vivo studies indicated that the tumor angiogenesis could be reduced by CXCL1 pathway blocking." (PMID 33826043, 2021). "In addition, monocytes polarized to the M2 macrophage phenotype upregulate PD-L1 and elaborate cytokines, such as MCP-3 and CXCL1, which further enhance immune infiltration, the induction of angiogenesis, and the recruitment of myeloid cells into the tumor microenvironment." (PMID 33509150, 2021). "Chemoattractants such as CXCL1 may help in recruiting non-malignant supportive cells such as neutrophils, which have ample functions as tumor-associated neutrophils (TANs) in the tumor environment." (PMID 34771518, 2021). "Therefore, it is possible that NDN isolated from 4T1 tumor-bearing mice may be less sensitive to the direct effect of CXCL1, as they are already primed by such high levels of this chemokine." (PMID 34680231, 2021). "Notably, CXCL1 is the key chemokine in the tumor microenvironment by recruiting MDSCs28." (PMID 34108444, 2021). "Therefore, we speculated that the high expression of CXCL1 in primary SKCM can inhibit tumor metastasis." (PMID 33767987, 2021). "Moreover, Cxcl1 expression was reported to be higher in immunotherapy-resistant tumor cell clones." (PMID 33572437, 2021). "The combination treatment caused increased secretion of CCL2, CCL21, CXCL1, CXCL2, CXCL5, CXCL9 and CXCL16, whereas the levels of CCL11, CCL17, CCL19, CCL22, CCL25, CCL27 and CX3CL1, which are associated with protumourigenic effects, were decreased in the tumours." (PMID 33014356, 2020). "Apparently, mGluR1 signaling has a direct effect on tumor cell growth and survival but it also increases inflammation within the tumor microenvironment by upregulating the production of inflammatory chemoattractants such as CXCL1, IL-6, and IL-8 and inducing neutrophil transmigration." (PMID 32973771, 2020). "Therefore, metformin may play an anti-tumor role by reducing the accumulation of MDSCs in the TME through AMPK/DACH1/CXCL1 axis." (PMID 33027968, 2020). "The serum CXCL1 may be a novel tumor marker for OC diagnosis." (PMID 32326946, 2020). "Moreover, in a study using TAMs excised from a MMTV-PyMT tumor model and monocytic cells, the overall conclusion was that macrophages released CXCL1, which via NF-κB activation has induced the transcription of the EMT regulator SOX4, leading to EMT and metastasis." (PMID 33585241, 2020). "Notably, CXCL1 has been shown to recruit tumor-adjacent immune cells to support tumor development, providing a mechanistic form of positive feedback, and can likewise recruit other stromal cells to create a premetastatic niche that supports cancer growth and metastasis." (PMID 33256011, 2020). "Interestingly, CXCL1 was mainly expressed in stromal cells around the tumor than in tumor cells." (PMID 31999765, 2020). "Moreover, in terms of M staging, the median values of CXCL1 expression were relatively higher in M0 staging than in M1 staging, and for the tumor stage, the median values of INHBA expression and riskScore were significantly elevated in stage III-IV than in stage I-II." (PMID 32788867, 2020). "In particular, the significant increase in circulating CXCL1, along with the correlation of the number of blood neutrophils with the tumor size, may be related to the recruitment of tumor entrained neutrophils (TENs) from the bone marrow into possibly other organs." (PMID 31114758, 2019).
tumor (continued). "Further, conditioned medium from MSCs exposed to tumor cell-derived extracellular vesicles (EVs) caused an upregulation in STAT3 phosphorylation and proliferation of CCA cells, possibly by secretion of CCL2/MCP1, CXCL1/GRO-α, CXC3CL1/Fractalkine, IL-6, and PDGF-AA." (PMID 31921870, 2019). "Additionally, TAMs-secreted CXCL1 could recruit MDSCs into the tumor microenvironment, which secreted chemokines including S100A8/9 that enhance cancer cell survival, chemoresistance, metastasis, and pre-metastatic niche formation." (PMID 31803057, 2019). "Inflammatory CC (CCL2, CCL3, CCL5) and CXC (CXCL1, CXCL2, CXCL5, CXCL6, and CXCL8) chemokines recruit at the tumor site CCR2+ monocytes and CXCR2+ neutrophils that differentiate into tumor associated macrophages (TAMs) and tumor associated neutrophils (TANs), exerting pro- or anti-tumoral role." (PMID 30894861, 2019). "Thus, we investigated if the reduction of tumor volume induced by naproxen-HTBA could be related to a down-regulation of CXCL1 production." (PMID 30800067, 2019). "Thus, we assessed whether increases in TNF-α, CXCL8, and CXCL1 would also be observed during selection of tumor cells for survival in increasing concentrations of docetaxel." (PMID 28915246, 2017). "However, CXCL1 was far less expressed in tumor cells KYSE-30 and KYSE-150." (PMID 28518141, 2017). "Given the limitations that our obese and non-obese patient cohorts were small, and follow-up duration relatively short, our data suggest that epithelial CXCL1 expression and CXCR1-positive tumour stroma in obese patients may be associated with more aggressive disease features." (PMID 27241286, 2016). "Additionally, autocrine and paracrine of CXCL1 can also promote tumor invasion and metastasis." (PMID 27446967, 2016). "Further association between the CXCL1/CXCR1 gradient and patient outcome was obtained from our analysis of the tissue microarray: high epithelial CXCL1 and high stromal CXCR1 expression was observed for 100% of analysed tumours from patients who eventually deceased." (PMID 27241286, 2016). "Moreover, given that combined blockade of pathways through CXCL1 and Mincle reduced tumor growth more effectively than those in Mincle blockade alone, a therapy aimed at both CXCL1 and Mincle could be the alternative way." (PMID 27551523, 2016). "Finally, tumor-derived prostanoids directly induce the production by myeloid cells of known cancer-promoting factors such as IL-6, CXCL1, and G-CSF, effectively shifting the tumor microenvironment from one favorable to tumor eradication to one that has pro-tumor activity." (PMID 26343581, 2015). "More effective tumor suppression may be achieved with dual CXCL1 and CXCR2 blockage." (PMID 26104296, 2015). "Finally, upon tumor fibroblast interaction the massive induction of chemokines such as CXCL1 and CXCL6 in FBs might be responsible for increased recruitment of a monocytic cell line (THP-1) in a transwell assay." (PMID 25919140, 2015). "After 5 weeks of continuous CXCR2 blockade, we could not only observe a marked reduction in tumour vascularization but importantly tumour incidence and overall tumour burden were reduced, suggesting that CXCL1 is crucial for tumour development at early stages in Stat3ΔLep/ΔLep: KrasG12D/+ mice." (PMID 25734337, 2015). "As the binding receptors CXCR1 and CXCR2 are expressed on myeloid derived cells and carcinoma cells, CXCL1 expression in CAFs may serve to regulate paracrine signaling interactions with immune cells and cancer cells to promote chemo-resistance and tumor progression." (PMID 25344051, 2014). "Moreover, increased CXCL1 levels correlated with advanced tumor stage and lymph node metastasis." (PMID 24971349, 2014). "To check whether NFκB-CXCL1 pathway would be involved in tumor cell inoculation-induced CXCL1 upregulation and pain hypersensitivity, we first checked NFκB activation in the spinal cord after tumor cell inoculation." (PMID 24580964, 2014).